BCL2L1 (BCL2 like 1)
Diseases named in the same sentence as BCL2L1 in open-access papers (continued):
Sharing a sentence is not in itself a finding about the gene and the disease.
tumor (continued). "TBX5 and YES-associated protein 1 (YAP1) form a complex with β-catenin, which localizes and activates BCL2 Like 1 (BCL2L1) and Baculoviral IAP Repeat Containing 5 (BIRC5), thereby enhancing the anti-apoptotic effect on tumor cells." (PMID 38965548, 2024). "Thus, BCL2L1 may contribute not only to tumor development but also to therapy resistance." (PMID 38316463, 2024). "BCL2L1 (BCL-XL), on the other hand, was most highly expressed by MBG3, while NB tumours showed average expression." (PMID 38942989, 2024). "The BCL2L1, CAV1, KDELR3 and YWHAZ expression levels were upregulated in the tumour tissues and downregulated in the healthy pancreatic tissues." (PMID 38303549, 2024). "Overall, these results indicated that silencing of HIGD2A inhibited tumor cell proliferation and survival partially by blocking the MAPK/ERK pathway and repressing the expression of BCL2L1." (PMID 37041638, 2023). "We observed amplifications in chromosome arm 20q (chr20q) in 74/373 tumours (19.8%), which includes SRC, TOP1, BCL2L1, ZNF217, AURKA, GNAS and ARFRP1." (PMID 37666855, 2023). "When comparing the gene expression signature of poorly differentiated (G3) tumours with the moderately differentiated (G2) ones, the downregulation of RELA, NOD1, CASP8, BCL2L1, ELK1, and IKBKB was found." (PMID 36433652, 2022). "A decrease in the levels of RELA, NOD1, CASP8, BCL2L1, ELK1, and IKBKB was identified in the poorly differentiated (G3) tumours compared with the moderately differentiated (G2) ones." (PMID 36433652, 2022). "In the univariable Cox analysis, clinical tumor stage, age, and the expression levels of NFE2L2, ITGAV, GET4, FERMT2, CRB3, CDH2, and BCL2L1 were prognostic factors for OS." (PMID 33850477, 2021). "B4GALT4, BCL2L1, COPG1, CRB3, GET4, and TFRC showed almost the same expression levels between tumor and normal tissues." (PMID 33850477, 2021). "Some NF-κB target genes such as CCND1, BCL2L1 and GADD45B and ICAM1 which are responsible for proliferation, anti-apoptosis and adhesion were also upregulated in the tumor tissues." (PMID 33144684, 2021). "RAs within the tumor drive upregulation of survival genes in tumor cells, in particular, GSTA5, BCL2L1, and TWIST1." (PMID 34859239, 2021). "Drawing insights into the functions of these genes, several tumor proliferation-related genes (EGFR, NOTCH1, and MAP2K1) and the anti-apoptosis related genes (BCL2L1, XIAP) were detected." (PMID 33637972, 2021). "As expected, our data showed that δ‐catenin knockdown suppressed β‐catenin nuclear localization and subsequent alteration of Bcl2L1 and cyclin D1 level in both ACHN cells and ACHN‐derived xenograft tumor tissue." (PMID 31991069, 2020). "We identified six TAA protHLAIp that were exclusively detected in the tumor tissue of C3N-02289 (BIRC5, TERT, FAP, SPAG4, MAGEA9, and BCL2L1)." (PMID 32157095, 2020). "The analyses of circulating tumor DNA further showed that compromised SWI/SNF complex facilitated BCL2L1 transcription and the upregulation of BCLXL." (PMID 32545704, 2020). "Among the genes significantly affected by ionizing radiation, we discovered BCL2L1, a gene involved in the regulation of apoptosis, and CYB5D2 that inhibits cell proliferation and has a putative tumor suppressor activity." (PMID 32883354, 2020). "Among these genes, many are involved in tumour suppression [e.g. RB1], apoptosis [e.g. BCL2L1], the cell cycle [e.g. CCND1, CCND2] or protein kinases [e.g. KIT, GSK3‐β]." (PMID 28539478, 2017). "Somatic CNVs in BCL2L1 and MCL1 genes were tested in tumor tissues from 516 NSCLC patients in southern China; afterward, survival analyses were conducted with overall survival (OS) as outcome." (PMID 27264345, 2016). "After further mapping the gene expression data of the matched tumor samples in the TCGA CRC cohort, we found that there was a concordant copy number gain and an up-regulation of BCL2L1." (PMID 27477450, 2016).
tumor (continued). "It has been shown that miR-221 and miR-222 functionally target and inhibit the expression of tumor suppressor genes (such as CDKN1B/p27 and CDKN1C/p57) and oncogenes (such as BCL2L1 and ER) in various cancers, including glioblastoma, hepatocellular carcinoma, breast cancer, and PCa." (PMID 37370750, 2023). "Moreover, a decrease in the levels of RELA, NOD1, CASP8, BCL2L1, ELK1, and IKBKB was identified in poorly differentiated tumours compared to moderately differentiated tumours." (PMID 36433652, 2022). "Despite the increase in phospho-SRC signal in DEXA treated tumours, we did not detect a significant increase in BCL2L1 and MCL1 expression." (PMID 33478100, 2021). "We found that BCL2L1 expression levels were significantly upregulated in the CRC tumor tissues and cell lines compared with the adjacent nontumor tissues (p < .05)." (PMID 32064615, 2020). "Therefore, we analyzed the levels of expression of IL-2, IL-2RA and CD27 together with CD40LG and the anti-apoptotic regulator BCL2L1 on CD8+ TILs isolated from peripheral blood and tumor tissues of Bhi OPSCC patients (n = 4; Cohort 3)." (PMID 31623665, 2019). "We hypothesize that miR-375 exerts its tumor suppressive role partly by acting as an upstream regulator of BIRC5 and BCL2L1 through the targeting of YAP1." (PMID 24892549, 2014). "Importantly, similar to short-term Olaparib treatment, RT-PCR analysis of parental and Olaparib-resistant A2780, OVCAR8, and PEO1 cells showed mRNA upregulation of several essential tumor-promoting genes, such as MMP9, VEGFA, CCND1, and BCL2L1, which are known STAT3 target genes." (PMID 34956861, 2021). "Il6 deficiency also reduced hepatic mRNA levels of Stat3 target genes (Birc5, Bcl2l1 and Ccnd1), cyclins (Ccna2, Ccnb1, Ccnb2), and markers of proliferation (Mki67) and HCC (Afp) in livers from FGF19-expressing mice, further demonstrating the role of IL-6 in mediating FGF19-driven tumour growth." (PMID 28508871, 2017). "However, active effectors (BAX and BAK) or initiator (PMAIP1, BIK and BID) cannot lead to apoptosis in tumours, and these pro‐apoptotic proteins may be sequestered by guardians (BCL2 and BCL2L1) that have more potent enhancer activity to propel the anti‐apoptotic mechanisms." (PMID 32419250, 2020). "In patient-derived cell lines, we did not observe a clear trend in BCL2L1 (BCL-xL gene) nor HRK mRNAs, probably due to higher inter-tumor variability compared to the MCL-1:NOXA adaptation." (PMID 40113795, 2025). "We consistently found that BCL2L1 and XIAP were highly expressed specifically in tumor cells but not in non-tumor cells." (PMID 39122703, 2024). "And we could not show the question which the inverse correlation between BCL2L1 and apoptosis in LST is occurred also in other types of tumor." (PMID 26048755, 2015). "TNFSF10 and BCL2L1 were other selected genes that were considered expression-driven dependency genes 4, and TNFSF10 belonged to the family of tumor necrosis factor (TNF) ligands that could induce apoptosis in tumor cells but normally did not kill healthy cells." (PMID 33850477, 2021).
infection (86 papers, 2007 to 2025). The state of being infected such as from the introduction of a foreign agent such as serum, vaccine, antigenic substance or organism. "On the other hand, in later infection stages BCL2L1, a pro-survival member of the BCL2 family, showed consistently decreased expression in E. coli K12 compared to MAH infected MDMs (P<0.015, unpaired t test)." (PMID 21629653, 2011). "Furthermore, anti-apoptotic genes, GADD45B and CFLAR, and the IAP family members (BIRC2 and BCL2L1) were upregulated early or late after DTMUV infection." (PMID 32897243, 2020). "Many genes associated with the cell death such as tumour necrosis factor receptor (Tnfrsf1a), inhibitor of kappaB kinase (Ikbkg), kinases (Cd82 and Cdk2), and apoptosis regulator (Bcl2l1 and Birc2) were only up-regulated in WT infection and showed no expression in BM16 infection." (PMID 27634329, 2016).
hematological malignancies (41 papers, 2014 to 2025). "BCL2L1 upregulation is a resistance factor of MCL1 inhibitor response in solid tumors and hematological malignancies." (PMID 39846250, 2025).
neurodegenerative disease (7 papers, 2016 to 2024). A disorder of the central nervous system characterized by gradual and progressive loss of neural tissue and neurologic function. "Recently, changes in miRNA expression have also been linked to various neurodegenerative diseases, providing new hope for diagnosing and differentiating DLB; for example, the pathological link between the genes BCL2L1 and PIK3R2 has been further supported." (PMID 39116438, 2024).
blood cancer (6 papers, 2019 to 2024). "In FVPTC samples, LGALS3, an IA gene, is strongly associated with genes associated with blood cancers (RUNX1, BCL2L1, CBFB, and TNFRSF1A), suggesting a strong immune association in LGALS3 activity." (PMID 31443155, 2019).
neurological diseases (2 papers, 2020 to 2022). "Bcl2 family-related proteins [Bcl2, Bcl-xL (also known as Bcl2l1), Bax and Bak1] play an essential role in the neuronal apoptotic pathway in various neurological diseases." (PMID 32540990, 2020).
CNS tumors (1 paper, 2025). "cg00300298 site within BCL2L1 is hypermethylated in pediatric CNS tumors." (PMID 39846250, 2025).
BCL2L1 also shares sentences with these, for which no sentence is quoted: Cerebral ischemia (25 papers); ischemia (20); thyroid cancer (16); diffuse large B-cell lymphoma (15); medulloblastoma (15); chronic myeloid leukemia (14); mesothelioma (13); oral cancer (13); neutropenia (12); metastatic melanoma (11); sarcoma (11); skin cancer (11); myeloid leukemia (10); myocardial infarction (10); nasopharyngeal carcinoma (10); renal carcinoma (10); hematologic cancer (9); Hyperglycemia (9); Parkinson disease (9); adenocarcinoma (8); colon adenocarcinoma (7); colorectal tumors (7); esophageal cancer (7); insulinoma (7); myeloproliferative neoplasm (7); Obesity (7); T cell lymphomas (7); Burkitt lymphoma (6); glaucoma (6); laryngeal carcinoma (6).
A further 264 diseases each share a sentence with BCL2L1 in 6 papers or fewer.